MICU1 (mitochondrial calcium uptake 1)
Diseases named in the same sentence as MICU1 in open-access papers (continued):
Sharing a sentence is not in itself a finding about the gene and the disease.
cardiac hypertrophy (8 papers, 2020 to 2025). "Increased MICU1 expression has also been implicated in protecting against various cardiovascular conditions, including cardiac hypertrophy and hypoxia-induced myocardial injury." (PMID 40422231, 2025). "We found that endothelial-specific MICU1 knockout caused disruption of myocardial microvascular barrier function in diabetic mice, exacerbated cardiac hypertrophy and fibrosis, and significantly reduced cardiac function." (PMID 37592255, 2023). "Recently, activation of mitochondrial calcium uptake 1 (MICU1) induced by melatonin has been suggested as a mechanism underlying the protective effect of melatonin against cardiac hypertrophy." (PMID 34439517, 2021). "Taken together, these results supported the conclusion that reduced MICU1 causes abnormal mitochondrial morphology and function, resulting in oxidative stress and pathological cardiac hypertrophy." (PMID 33259334, 2020). "With genetic method, we found that MICU1 deficiency aggravated myocardial hypertrophy both in vivo and in vitro." (PMID 33259334, 2020). "MICU1 activation may be the mechanism underlying melatonin-induced protection against myocardial hypertrophy." (PMID 33259334, 2020). "Oxidative stress is a common mechanism underlying the pathological cardiac hypertrophy, and MICU1 might exert an antioxidant effect on hypertrophic growth stimulated by Ang-II." (PMID 33259334, 2020). "Taken together, these data suggested that endothelial cell MICU1 knockout aggravated the levels of cardiac hypertrophy and interstitial myocardial fibrosis and led to a further reduction in left ventricular function in diabetic mice." (PMID 37592255, 2023). "Mitochondrial calcium uptake 1 (MICU1), a Ca2+ binding protein residing in the intermembrane of mitochondria, was proved to be required in the regulation of cardiac hypertrophy." (PMID 35118147, 2021). "In summary, the present study provides evidence that downregulation of MICU1 aggravates cardiac hypertrophy, and enforced MICU1 attenuates myocardial hypertrophy via ameliorating mitochondrial injury and inhibiting ROS generation." (PMID 33259334, 2020). "Second, our genetic experiments found that MICU1 reduction exacerbated Ang-II-induced cardiac hypertrophy both in vivo animal and in vitro cellular models; in contrast, the enforced expression of MICU1 inhibited the development of cardiac hypertrophy." (PMID 33259334, 2020). "MICU1 expression was depressed in hypertrophic myocardia and MICU1 knockdown aggravated Ang-II-induced cardiac hypertrophy in vivo and in vitro." (PMID 33259334, 2020). "Taken together, these findings revealed that MICU1 was sufficient to blunt Ang-II-induced cardiac hypertrophy in vivo." (PMID 33259334, 2020). "Collectively, our results demonstrate that MICU1 attenuates Ang-II-induced cardiac hypertrophy by inhibiting mitochondria-derived oxidative stress." (PMID 33259334, 2020). "To examine concrete role of MICU1 in Ang-II-induced cardiac hypertrophy, we knocked down MICU1 in WT mice and hypertrophic mice by intramyocardial injection of MICU1-targeted small interfering RNA (siRNA)." (PMID 33259334, 2020). "Fourth, melatonin administration increased the expression of PGC-1α/MICU1 and, furthermore, MICU1 was required for the protective effects of melatonin against Ang-II-induced cardiac hypertrophy." (PMID 33259334, 2020). "Moreover, we demonstrated that endothelial cell MICU1 knockout exacerbated the levels of cardiac hypertrophy and interstitial myocardial fibrosis and led to a further reduction in left ventricular function in diabetic mice." (PMID 37592255, 2023). "Conclusively, our study suggested that melatonin could effectively alleviate cardiac hypertrophy through increasing MICU1." (PMID 33259334, 2020). "Therefore, our observations provided evidence that downregulated MICU1 in hypertrophic myocardium contributes to Ang-II-induced cardiac hypertrophy." (PMID 33259334, 2020).
cardiac hypertrophy (continued). "In contrast, upregulation of MICU1 attenuated cardiac hypertrophy." (PMID 33259334, 2020). "Melatonin exerts a protection effect on cardiac hypertrophy through PGC-1α/MICU1 pathway." (PMID 33259334, 2020). "Collectively, these results indicated that MICUs, especially mitochondrial MICU1, might take part in the Ang-II-induced cardiac hypertrophy." (PMID 33259334, 2020). "Notably, we found that AAV9-MICU1 specifically upregulated the expression of MICU1 in CMECs of diabetic mice, which inhibited nitrification stress, inflammatory reaction, and apoptosis of the CMECs, ameliorated myocardial hypertrophy and fibrosis, and promoted cardiac function." (PMID 37592255, 2023). "However, it is unclear whether MICU1 attenuates mitochondrial stress in angiotensin II (Ang-II)-induced cardiac hypertrophy or if it has a role in the function of melatonin." (PMID 33259334, 2020). "Furthermore, melatonin increased mitochondrial ATP level, reduced superoxide generation, and attenuated BNP expression in the corresponding controls, but not MICU1-deficient mice subjected to cardiac hypertrophy." (PMID 33259334, 2020). "However, it remains ambiguous whether MICU1 is involved in melatonin’ protection in cardiac hypertrophy." (PMID 33259334, 2020). "Hence, MICU1 was indispensable to melatonin-induced protection against cardiac hypertrophy." (PMID 33259334, 2020). "Thus, we hypothesized that MICU1 might serve as the major molecule in the development of myocardial hypertrophy." (PMID 33259334, 2020). "Melatonin ameliorated excessive ROS generation, promoted mitochondrial function, and attenuated cardiac hypertrophy in control but not MICU1 knockdown NMVMs or mice." (PMID 33259334, 2020). "Similar results were obtained on db/db diabetic mice, where over-expression of MICU1 (mitochondrial calcium uptake 1), the regulatory subunit of MCU, inhibits the development of DCM (through the enhanced cardiac function, reduced myocardial fibrosis and cardiac hypertrophy)." (PMID 35887211, 2022). "It is acknowledged that melatonin has therapeutic effects in cardiovascular diseases, but whether it can influence MICU1 in Ang-II-induced cardiac hypertrophy is not identified." (PMID 33259334, 2020).
diabetes (4 papers, 2018 to 2023). "Further research is required to elucidate the underlying mechanism by which MICU1 improves diabetes." (PMID 37592255, 2023). "Our previous study has provided that the deficiency in mitochondrial calcium uptake due to the down-regulation of MICU1 expression in diabetes cardiomyocytes leads to myocardial oxidative damage, thereby promoting the occurrence and progression of DCM." (PMID 37592255, 2023). "MICU1 is a key molecule that regulates mitochondrial calcium homeostasis, which is closely related to myocardial injury in diabetes." (PMID 37592255, 2023). "In vivo and in vitro studies confirmed the important role of endothelial MICU1 in myocardial microvascular injury in diabetes." (PMID 37592255, 2023). "Our data revealed that diabetes significantly downregulated VE-cadherin fluorescence in myocardial microvessels, and endothelial MICU1 knockout further inhibited the expression of VE-cadherin in diabetic MICU1ecKO mice." (PMID 37592255, 2023). "Can the upregulation of MICU1 improve myocardial microvascular injury in diabetes?" (PMID 37592255, 2023). "Furthermore, our study showed that THF treatment attenuated diabetes by regulating adipocyte mitochondrial function by AMPK/MICU1 pathway in vivo and in vitro." (PMID 37337224, 2023). "However, it remains inconclusive whether this therapeutic effect is solely attributed to the direct influence of MICU1 or if it is a secondary consequence of improved diabetes." (PMID 37592255, 2023). "Diabetes significantly upregulated ICAM-1 levels, and endothelial cell MICU1 knockout further intensified this change in diabetic MICU1ecKO mice." (PMID 37592255, 2023). "Ca2+ is an important regulatory ion and mitochondrial dysfunction caused by the imbalance of mCa2+ homeostasis is considered to be a significant pathological mechanism of diabetes, while MCU/MICU1 is a key molecule that regulates mCa2+ uptake." (PMID 37337224, 2023). "Our in vitro experiments found that the upregulation of MICU1 expression by Ad-MICU1 reduced the nitration products, apoptosis, and inflammation in CMECs cultured with HGHF, which indicated that MICU1 may reduce diabetes-induced endothelial cell damage by inhibiting nitrification stress." (PMID 37592255, 2023). "Additionally, our investigation revealed that MICU1 overexpression enhanced the glucose tolerance of diabetic mice, indicating that MICU1 overexpression directly contributes to the amelioration of DCM, while also benefiting from the concurrent improvement of diabetes." (PMID 37592255, 2023). "However, whether MICU1 participates in the development of myocardial microvascular injury in diabetes by affecting the function of CMECs has not been reported." (PMID 37592255, 2023).
melanoma (4 papers, 2015 to 2025). A malignant, usually aggressive tumor composed of atypical, neoplastic melanocytes. "Experiments in human melanoma cell lines have also indicated that RPS3 has a role in stabilizing the Ca2+ gatekeeper mitochondrial calcium uptake 1 (MICU1)." (PMID 40940922, 2025). "Prior studies have revealed that RPS3 regulates melanoma cell proliferation and apoptosis primarily by modulating Ca2+ signaling and MiCU1-dependent mitochondrial pathways." (PMID 38911376, 2024). "Our results therefore demonstrated that RPS3 regulated melanoma growth through the modulation of the Ca2+/MICU1 dependent mitochondrial signaling and suggest that RPS3 is a potential therapeutic target for melanoma treatment." (PMID 26336993, 2015). "Notably, also EMRE and MICU1 were decreased in the resistant lines to some extent, suggesting that mitoCa2+ is an important parameter of acquired therapeutic resistance in melanoma." (PMID 36156348, 2022). "Our results therefore demonstrate that RPS3 regulates melanoma growth through the modulation of the Cyto C/Ca2+/MICU1 dependent mitochondrial signaling and suggest that RPS3 is a potential therapeutic target for melanoma treatment." (PMID 26336993, 2015).
diabetic cardiomyopathy (3 papers, 2023 to 2025). Diabetic cardiomyopathy is a disorder of the heart muscle in people with diabetes. "To identify potential strategies for the treatment of diabetic cardiomyopathy, we evaluated the potential mechanisms underlying the cardioprotective effects of MICU1 in CMECs." (PMID 37592255, 2023). "In the context of diabetic cardiomyopathy, the role of mCUP and its regulatory subunit, mitochondrial calcium uptake protein 1 (MICU1), has emerged as a critical factor in Ca2+-transport." (PMID 40564057, 2025). "To examine the role of endothelial MICU1 in diabetic cardiomyopathy (DCM), we used endothelial-specific MICU1ecKO mice to establish a diabetic mouse model and evaluate the cardiac function." (PMID 37592255, 2023). "MICU1 has also been found to attenuate cardiac microvascular injury of diabetic cardiomyopathy." (PMID 40166941, 2025).
head and neck squamous cell carcinoma (3 papers, 2020 to 2024). A squamous cell carcinoma that arises from any of the following anatomic sites: lip and oral cavity, nasal cavity, paranasal sinuses, pharynx, larynx, and salivary glands. "In head and neck squamous cell carcinoma, MiCU1 expression is elevated, and inhibiting MiCU1 disrupts mitochondrial calcium homeostasis and membrane potential stability, thereby inhibiting apoptosis and reducing Bcl-2 expression." (PMID 38911376, 2024). "Kong and colleagues demonstrated that the depletion of HOTAIR promoted the apoptosis of head and neck squamous cell carcinoma through the induction of mitochondrial calcium uptake 1 (MICU1)." (PMID 32331347, 2020).
hepatocellular carcinoma (3 papers, 2020 to 2024). A malignant tumor that arises from hepatocytes. "Further investigation is needed to elucidate the mechanisms through which MiCU1/2 influences the development of hepatocellular carcinoma cells." (PMID 38911376, 2024). "Similarly, in hepatocellular carcinoma (HCC) cells, the upregulation of MCU and the downregulation of MICU1 led to an increased basal mCa2+ compared to the control cells." (PMID 34307407, 2021).
myocardial infarction (3 papers, 2021 to 2025). Gross necrosis of the myocardium, as a result of interruption of the blood supply to the area, as in coronary thrombosis. "MR analysis also found a trend where increased expression of MICU1 was weakly associated with a decreased risk of myocardial infarction (OR = 0.94) and angina pectoris (OR = 0.93), although these associations were not statistically significant." (PMID 40166941, 2025). "Tom70 is additionally involved in mitigating myocardial infarction and ischemia/reperfusion injury through interactions with melatonin and mitochondrial calcium uptake 1 (MICU1) protein." (PMID 34064787, 2021).
Ataxia (2 papers, 2018 to 2021). Ataxia refers to impaired coordination of voluntary muscle movement. "MICU1’s function as a gatekeeper is also important in vivo to prevent mitochondrial Ca2+ overload, as evidenced in MICU1-knockout animals, developing ataxia and muscle fatigue associated with elevated mitochondrial Ca2+ levels and reduced ATP levels." (PMID 29491433, 2018). "In more detail, the characterization of MICU1-/- transgenic mice reveals that, despite partial postnatal mortality, the viable animals show marked ataxia and muscle weakness, a phenotype which is reminiscent of that of human patients bearing MICU1 genomic mutation." (PMID 34071006, 2021).
atherosclerosis (2 papers, 2025). A disease characterized by the build-up of fatty material and calcium deposition in the arterial wall resulting in partial or complete occlusion of the arterial lumen. "Consequently, diminished MICU1 levels could potentially serve as a diagnostic biomarker for the presence of atherosclerosis or as predictive markers for the likelihood of severe future events, such as CABG." (PMID 40166941, 2025). "To validate the potential role of the SIRT3/SOD2 pathway in Micu1-regulated atherosclerosis, we analyzed SIRT3 expression and levels of acetylated SOD2 in aortic root sections of hypercholesterolemic Micu1ECKO and Micu1fl/fl mice." (PMID 40166941, 2025). "Specifically, endothelial Micu1 deletion aggravated, while endothelial Micu1 overexpression attenuated, vascular inflammation and atherosclerosis." (PMID 40166941, 2025). "This investigation has demonstrated that restoring MICU1 expression in ECs not only reduces vascular inflammation, but also helps prevent atherosclerosis." (PMID 40166941, 2025). "In the present study, we demonstrated that MICU1 is a crucial factor in suppressing endothelial inflammation and preventing the development of atherosclerosis." (PMID 40166941, 2025). "Our findings support MICU1 as an endogenous endothelial resilience factor that protects against vascular inflammation and atherosclerosis by maintaining mitochondrial Ca2+ homeostasis." (PMID 40166941, 2025). "As such, therapies aimed at maintaining optimal levels of MICU1 in vascular ECs present an alternative approach for managing atherosclerosis." (PMID 40166941, 2025). "In conclusion, our study highlights that MICU1 contributes to vascular resilience by preventing EC mitochondrial dysfunction, vascular inflammation, and atherosclerosis." (PMID 40166941, 2025). "In this study, we investigated the potential role of endothelial MICU1 in vascular inflammation and atherosclerosis by focusing on mitochondrial function, Ca2+ dynamics, and redox balance." (PMID 40166941, 2025). "Here, we report that endothelial MICU1 prevents vascular inflammation and atherosclerosis by maintaining mitochondrial homeostasis." (PMID 40166941, 2025). "Since inflammation drives atherosclerosis, we hypothesized that endothelial MICU1 may influence this process." (PMID 40166941, 2025). "This study focuses on how MICU1 regulates SIRT1 expression to influence atherosclerosis." (PMID 41329250, 2025). "In addition, EC-specific Micu1-knockout mice (Micu1ECKO) accelerated, while EC-specific Micu1 transgenic mice (Micu1ECTg) were protected against ROS generation, vascular inflammation, and atherosclerosis." (PMID 40166941, 2025). "Based on these findings, we propose that therapeutic strategies effective against atherosclerosis by targeting of MICU1 might also be beneficial for CAVS." (PMID 40166941, 2025). "Thus, MICU1 represents an endogenous resilience factor against vascular inflammation and atherosclerosis in the context of mitochondrial dysfunction." (PMID 40166941, 2025). "Thus, we hypothesize that MICU1 regulates vascular inflammation and atherosclerosis potentially through the SIRT3/SOD2/mROS pathway." (PMID 40166941, 2025). "However, the role of MICU1 in vascular inflammation and atherosclerosis remains unknown." (PMID 40166941, 2025). "In this study, we demonstrated the role of MICU1 in regulating SIRT3/SOD2 activity in the context of vascular inflammation and atherosclerosis." (PMID 40166941, 2025). "Similarly, gene set enrichment analysis (GSEA) showed that MICU1 depletion upregulated TNF signaling, TLR signaling, and atherosclerosis-related pathways." (PMID 40166941, 2025). "However, the precise role of endothelial MICU1 in vascular inflammation and atherosclerosis in vivo has not been reported." (PMID 40166941, 2025).
cardiomyopathy (2 papers, 2022 to 2023). A disease of the heart muscle or myocardium proper. "Twelve of the 52 mouse models identified with cardiomyopathy (Acadv1, Fxn, Mto1, Taco1, Hmgcs2, Mpv17, Opa1, Pnpla8, Tmem126b, Gpd2, Mpv17, Micu1) showed that the presence of cardiomyopathy can be dependent on the degree of stress." (PMID 37103033, 2023). "More specifically, restoring normal function of mitochondrial calcium uptake 1 (MICU1), which was confirmed to be downregulated in the hearts of diabetic mice via hyperlipidemia and hyperglycemia, was important for inhibiting the progression of cardiomyopathy." (PMID 35252405, 2022).
cognitive decline (2 papers, 2023). "Conversely, mutations in an MCU regulator, MICU1, which increase resting mitochondrial Ca2+ levels, caused neuromuscular disorders with cognitive decline, muscle weakness, and an extrapyramidal motor disorder." (PMID 36935171, 2023). "Likewise, mutations in an MCU regulator MICU1, which increases resting mitochondrial Ca2+ levels, caused neuromuscular disorders with cognitive decline, muscle weakness, and an extrapyramidal motor disorder." (PMID 36935171, 2023).
cognitive delay (2 papers, 2020). "Recessive variants in MICU1 produces elevations of creatine kinase with normal lactate levels and ETC activities, but induce a range of symptoms of muscle weakness, fatigue, cognitive delay, and facial dysmorphism." (PMID 33426505, 2020). "Biallelic pathogenic variants in MICU1 cause MPXPS, which classically presents with myopathy, developmental delay, and extrapyramidal signs." (PMID 32395406, 2020). "MPXPS, secondary to pathogenic variants in MICU1, can present with myopathy, developmental delay, and extrapyramidal symptoms." (PMID 32395406, 2020). "Here we report a female child with compound heterozygous variants in MICU1, who presents with typical symptoms of mitochondrial disease, including myopathy, ataxia, developmental delay, and generalized seizures, without an elevated lactate level." (PMID 32395406, 2020).